RNU6-54P (RNA, U6 small nuclear 54, pseudogene)
Synonyms: formerly RNU6-54
Gene: Small nuclear RNA gene on chromosome 13 (70,459,464 to 70,459,570, forward strand). Ensembl gene ENSG00000202433.
Homologues: Orthologues: chimpanzee U6 (98% identical), guinea pig U6 (71% identical), guinea pig U6 (64% identical). Paralogues in human: RNU6-454P (79% identical), RNU6-658P (79% identical), RNU6-1209P (78% identical), RNU6-268P (78% identical), RNU6-46P (78% identical), RNU6-480P (78% identical), RNU6-560P (78% identical), RNU6-98P (78% identical), RNU6-1 (77% identical), RNU6-11P (77% identical), RNU6-1309P (77% identical), RNU6-16P (77% identical), and 1287 more.